RNU6-413P (RNA, U6 small nuclear 413, pseudogene)
Gene: Small nuclear RNA gene on chromosome 10 (22,787,393 to 22,787,499, forward strand). Ensembl gene ENSG00000206842.
Homologues: Orthologues: chimpanzee U6 (100% identical), macaque U6 (96% identical), pig U6 (85% identical). Paralogues in human: RNU6-38P (89% identical), RNU6-468P (89% identical), RNU6-1011P (87% identical), RNU6-1227P (87% identical), RNU6-33P (87% identical), RNU6-46P (87% identical), RNU6-480P (87% identical), RNU6-698P (87% identical), RNU6-774P (87% identical), RNU6-1 (86% identical), RNU6-1024P (86% identical), RNU6-1026P (86% identical), and 1286 more.